SYCP2 (synaptonemal complex protein 2)
Diseases named in the same sentence as SYCP2 in open-access papers (continued):
Sharing a sentence is not in itself a finding about the gene and the disease.
cancer (continued). "Thus, SYCP2 may preferentially contribute to HR activity especially in cancer cells expressing SYCP2." (PMID 38383600, 2024). "Additionally, SYCP2, another important gene identified in our analysis, may contribute to HPV-associated cancer development, according to recent research." (PMID 34532284, 2021). "Of these, SYCP2 showed the most consistent fold change from baseline in premalignant tissue; aberrant expression of this protein may contribute to genetic instability during HPV‐associated cancer development." (PMID 26334652, 2015). "This disruption of ABL1-mediated SYCP2 phosphorylation impairs the recruitment of RAD51 to R-loops, leading to defective HR and increased genomic instability, which ultimately sensitizes cancer cells to treatment." (PMID 40918650, 2025). "The specific expression of SYCP2 in tumors and its contribution to DDR drug resistance makes the TC-HR pathway an attractive biomarker for cancer diagnosis, a predictor of the DDR drug response, and a potential target for therapy." (PMID 38383600, 2024). "We further show that this germ cell–like transcriptional program, even when reduced to the top two genes (CDKN2A and SYCP2), serves as a fingerprint of oncogenic HPVs with implications for early detection, diagnosis, and therapy of all HPV-driven cancers." (PMID 36213965, 2023). "In particular, SYCP2 and TAF7L, which have been shown in the past to be deregulated in cancer development." (PMID 36142875, 2022). "Multiple synaptonemal complex components, including SYCP1, SYCP2, SYCP3, SYCE1, and SYCE2, are expressed in cancers." (PMID 34830845, 2021). "The colony formation in SKOV3 wildtype or MUC16+ and OVCAR8 cells showed that lack of ABL1/SYCP2 expression or SYCP2 phosphorylation activity mediated by ABL1 would largely reduce the cancer cell survival." (PMID 40918650, 2025). "The phosphorylation of SYCP2 by ABL1, which stabilizes R-loops and facilitates RAD51 recruitment, suggests that ABL1 acts as a critical mediator between transcription and DNA repair in cancer cells." (PMID 40918650, 2025). "Given that many DDR drugs directly or indirectly induce DSBs and SYCP2 expression in cancer correlates with resistance to DDR drugs, we tested whether SYCP2 is involved in DSB repair." (PMID 38383600, 2024). "Together, our results suggest that aberrant expression of SYCP2 in cancer promotes TC-HR and confers DDR drug resistance, revealing a promising biomarker to predict the resistance to DDR drugs and a potential target overcome in cancer therapy in the future." (PMID 38383600, 2024). "We propose that, although SYCP2 is not normally expressed outside of meiosis, the aberrant expression of SYCP2 in cancer cells augments DSB repair and allows them to cope with genomic instability." (PMID 38383600, 2024). "Nevertheless, our in vitro experiments robustly demonstrate that SYCP2 expression modulates sensitivity to ABL1 inhibition and is required for DNA repair via TC-HR, supporting a model in which ABL1 inhibitors preferentially target SYCP2-high, platinum-resistant cancer cells." (PMID 40918650, 2025). "A limited number of correlative studies has shown aberrant SYCP2 expression in breast and papillomavirus-positive oropharyngeal carcinoma, while mechanisms, potential clinical, and therapeutic relevance of SYCP2 in cancers have not been well defined." (PMID 38383600, 2024). "Both functions of SYCP2 may contribute to the resistance of cancer cells to DDR targeted drugs regardless of the BRCA status." (PMID 38383600, 2024).
SYCP2 also shares sentences with these, for which no sentence is quoted: Cryptozoospermia (3 papers); bladder cancers (1); chronic fatigue syndrome (1); cutaneous T-cell lymphoma (1); Fanconi anemia (1); generalized epilepsy (1); head and neck squamous cell carcinoma (1); meningioma (1); oral cancer (1); osteosarcoma (1); panic disorder (1); personality disorder (1); Pseudoxanthoma elasticum (1); Sezary syndrome (1); somatotroph adenomas (1); squamous cell carcinoma (1).